GRIN2C (glutamate ionotropic receptor NMDA type subunit 2C)
Description:
Component of N-methyl-D-aspartate (NMDA) receptors (NMDARs) that function as heterotetrameric, ligand-gated cation channels with high calcium permeability and voltage-dependent block by Mg(2+). Participates in synaptic plasticity for learning and memory formation by contributing to the slow phase of excitatory postsynaptic current and long-term synaptic potentiation (By similarity). Channel activation requires binding of the neurotransmitter L-glutamate to the GluN2 subunit, glycine or D-serine binding to the GluN1 subunit, plus membrane depolarization to eliminate channel inhibition by Mg(2+). NMDARs mediate simultaneously the potassium efflux and the influx of calcium and sodium (By similarity). Each GluN2 subunit confers differential attributes to channel properties, including activation, deactivation and desensitization kinetics, pH sensitivity, Ca2(+) permeability, and binding to allosteric modulators.
Synonyms: GluN2C; NMDAR2C; NR2C
Tractability: Small molecule: an approved drug acts on it; a structure with a bound ligand is known; a high-quality ligand is known; it belongs to a druggable protein family. Antibody: UniProt places it where antibodies can reach, with high confidence; its Gene Ontology location is reachable by antibodies, with high confidence; UniProt predicts a signal peptide or a membrane-spanning region. PROTAC: a small molecule that binds it is known. Other modalities: a drug acting on it is in phase 2 or 3 trials.
Target class: Ion channel; Ionotropic glutamate receptor; Ligand-gated ion channel; NMDA receptor
Safety:
Unwanted effects reported when the protein is acted on. In parentheses: how it was acted on, where the effect was seen, and who reports it.
ataxia (inhibition, acute dosing; central nervous system, cardiovascular; source: Lynch et al. (2017))
convulsions (activation, acute dosing; central nervous system, cardiovascular; source: Lynch et al. (2017))
decreased convulsions (inhibition, acute dosing; central nervous system, cardiovascular; source: Lynch et al. (2017))
decreased memory (inhibition, acute dosing; central nervous system, cardiovascular; source: Lynch et al. (2017))
decreased pain (inhibition, acute dosing; central nervous system, cardiovascular; source: Lynch et al. (2017))
dizziness (inhibition, acute dosing; central nervous system, cardiovascular; source: Lynch et al. (2017))
drug abuse/dependence (inhibition, acute dosing; central nervous system, cardiovascular; source: Lynch et al. (2017))
impaired social interactions (inhibition, chronic dosing; central nervous system, cardiovascular; source: Lynch et al. (2017))
increased blood pressure (inhibition, acute dosing and activation, acute dosing; central nervous system, cardiovascular; source: Lynch et al. (2017))
increased heart rate (inhibition, acute dosing; central nervous system, cardiovascular; source: Lynch et al. (2017))
increased locomotor activity (inhibition, acute dosing; central nervous system, cardiovascular; source: Lynch et al. (2017))
increased then decreased heart rate (activation, acute dosing; central nervous system, cardiovascular; source: Lynch et al. (2017))
neurodegeneration (inhibition, chronic dosing; central nervous system, cardiovascular; source: Lynch et al. (2017))
neurotoxicity (inhibition, acute dosing; central nervous system, cardiovascular; source: Lynch et al. (2017))
pain (activation, acute dosing; central nervous system, cardiovascular; source: Lynch et al. (2017))
psychosis (inhibition, chronic or acute dosing; central nervous system, cardiovascular; source: Lynch et al. (2017))
stereotypy (inhibition, chronic dosing; central nervous system, cardiovascular; source: Lynch et al. (2017))
Gene: Protein-coding gene on chromosome 17 (74,842,022 to 74,861,767, reverse strand). Ensembl gene ENSG00000161509.
Subcellular location: Cell membrane; Postsynaptic cell membrane
Pathways (Reactome):
Neuronal System: Assembly and cell surface presentation of NMDA receptors; Long-term potentiation; Negative regulation of NMDA receptor-mediated neuronal transmission; Neurexins and neuroligins; Synaptic adhesion-like molecules; Unblocking of NMDA receptors, glutamate binding and activation
Gene Ontology:
Molecular function: NMDA glutamate receptor activity; protein binding; transmitter-gated monoatomic ion channel activity involved in regulation of postsynaptic membrane potential; ligand-gated monoatomic ion channel activity; monoatomic cation channel activity; monoatomic ion channel activity; signaling receptor activity
Biological process: calcium ion transmembrane import into cytosol; monoatomic cation transmembrane transport; brain development; excitatory chemical synaptic transmission; excitatory postsynaptic potential; glutamate receptor signaling pathway; ionotropic glutamate receptor signaling pathway; long-term synaptic potentiation; positive regulation of excitatory postsynaptic potential; positive regulation of synaptic transmission, glutamatergic; regulation of monoatomic cation transmembrane transport; regulation of neuronal synaptic plasticity; regulation of synaptic plasticity; synaptic transmission, glutamatergic; modulation of chemical synaptic transmission; monoatomic ion transport
Cellular component: NMDA selective glutamate receptor complex; plasma membrane; endoplasmic reticulum membrane; postsynaptic density membrane; postsynaptic membrane; glutamatergic synapse; membrane; organelle
Genetic constraint (gnomAD): Loss-of-function variants: 60 observed, 63.94 expected, observed/expected ratio (o/e) 0.94, 90% interval 0.76 to 1.16. The synonymous counts are far from expectation, so gnomAD's model fits this gene poorly and the ratio says little. Missense variants: 1,188 observed, 1,171.9 expected, observed/expected ratio (o/e) 1.01, 90% interval 0.97 to 1.06. Synonymous variants: 611 observed, 503 expected, observed/expected ratio (o/e) 1.21, 90% interval 1.14 to 1.3.
Homologues: Orthologues: chimpanzee GRIN2C (99% identical), macaque GRIN2C (97% identical), dog GRIN2C (90% identical), mouse Grin2c (89% identical), rat Grin2c (88% identical), pig GRIN2C (85% identical), guinea pig GRIN2C (81% identical), zebrafish grin2ca (58% identical), zebrafish grin2cb (57% identical), tropical clawed frog grin2c (55% identical), Drosophila melanogaster Nmdar2 (22% identical), Caenorhabditis elegans nmr-2 (20% identical), and 37 more. Paralogues in human: GRIN2D (47% identical), GRIN2A (44% identical), GRIN2B (43% identical), GRIN3B (21% identical), GRIN3A (19% identical), GRIN1 (17% identical), GRIA4 (16% identical), GRIA2 (16% identical), GRIK3 (16% identical), GRIA1 (16% identical), GRIK2 (16% identical), GRIK1 (16% identical), and 5 more.
Diseases named in the same sentence as GRIN2C in open-access papers:
GRIN2C is named in the same sentence as 44 diseases in open-access papers, as found by Europe PMC text mining. Sharing a sentence is not in itself a finding about the gene and the disease. The quoted sentences say what the papers report.
schizophrenia (12 papers, 2012 to 2024). A major psychotic disorder characterized by abnormalities in the perception or expression of reality. "Additionally, ultra-rare variants with loss of function in GRIN2C may increase the possible risk of schizophrenia." (PMID 35562887, 2022). "GRIN1, GRIN2A, GRIN2B, GRIN2C, and GRIN2D all encode subunits of the N-methyl-D-aspartate receptor (NMDAR), which has been shown to be involved in the development of schizophrenia." (PMID 34946799, 2021). "Reduced expression of the obligatory NMDAR subunit GluN1 (also known as NR1; encoded by GRIN1) and also of GluN2C (NR2C, encoded by GRIN2C) has been reported in post-mortem prefrontal cortex tissue of schizophrenia patients." (PMID 31824347, 2019). "The molecular characterization of postmortem brains from SCZ patients established a significant reduction in GRIN2C mRNA levels in the dorsolateral prefrontal cortex (DLPFC) tissue, which may lead to altered NMDAR stoichiometry and endogenous NMDAR deficit in schizophrenia." (PMID 39596430, 2024).
epilepsy (6 papers, 2010 to 2023). A brain disorder characterized by episodes of abnormally increased neuronal discharge resulting in transient episodes of sensory or motor neurological dysfunction, or psychic dysfunction. "Although Grin2c gene has not been related to epileptogenic processes, the subunit GRIN2A appears to be associated with the broadest and best characterized phenotypic spectrum, including a variety of disorders of the epilepsy aphasia spectrum and developmental and epileptic encephalopathy." (PMID 32528245, 2020).
Alzheimer disease (3 papers, 2013 to 2025). A progressive, neurodegenerative disease characterized by loss of function and death of nerve cells in several areas of the brain leading to loss of cognitive function such as memory and language. "Further research is necessary to determine the prevalence of genetic variants in the GRIN2C gene in late-onset Alzheimer's disease." (PMID 39810256, 2025). "In conclusion, this study presents findings on a family in which late-onset Alzheimer's disease is associated with the p.(Ala1072Val) variant in the GRIN2C gene." (PMID 39810256, 2025).
diabetes (2 papers, 2009 to 2013). "GRIN2C mRNA increased after 4 weeks of diabetes, but qRT-PCR of the entire retina cannot distinguish whether ganglion cells or amacrine cells were responsible." (PMID 23878504, 2013). "With the exception of GRIN2C, the NMDA receptor subunits showed significantly reduced mRNA expression after 12 weeks of diabetes." (PMID 23878504, 2013). "However, in contrast to the results of this study, another study using Wistar rats found that GRIN1 mRNA expression was increased after 1 and 4 weeks of diabetes and did not change after 12 weeks, and GRIN2C mRNA levels did not change at any time point." (PMID 23878504, 2013).
Anxiety (1 paper, 2026). Intense feelings of nervousness, tension, or panic often arise in response to interpersonal stresses. "Consistent with this, GEG also attenuated expression of excitotoxic N-methyl-D-aspartate (NMDA) receptor subunits GRIN2B and GRIN2C in the frontal cortex and hypothalamus, thereby reflecting impaired neuroplasticity and neurotoxicity that have been implicated in pain hypersensitivity and anxiety." (PMID 41515464, 2026). "Examining the mRNA SLC1A2, SLC1A3, GRM5, GRIN2B, GRIN2C, GRIA1, CHRNA7, 5-HT2A, and 5-HT3A offers insight into the neurotransmission systems implicated in NP-related anxiety." (PMID 41515464, 2026).
Ataxia (1 paper, 2022). Ataxia refers to impaired coordination of voluntary muscle movement. "Compared to the uninjured mice, we found that the mRNA expression levels of Gria3, Gria4, Grin2b, and Grin2c were markedly increased in DCN at day 7 post-SNC in non-ataxia control and ataxia mice." (PMID 36064798, 2022).
brain injuries (1 paper, 2024). "In addition, grin2c levels have been shown to decline following traumatic brain injuries, which is consistent with our study on SCI." (PMID 37864744, 2024).
Hepatic steatosis (1 paper, 2025). Steatosis is a term used to denote lipid accumulation within hepatocytes. "Together, the overexpression of the three genes TENM2, GRIN2C, and ACACB in the CC group would indicate a greater synthesis of fats in the liver, which could lead to the accumulation of these and produce hepatic steatosis." (PMID 40160973, 2025).
mental disorder (1 paper, 2019). A disease that has its basis in the disruption of mental process. "Using knockout-first strains for the GRIN2C and GRIN2D produced on pure C57BL/6N strain, we compared the effect of partial or complete ablation of GluN2C and GluN2D subunit on various behaviors relevant to mental disorders." (PMID 31110197, 2019).
neurological disorders (4 papers, 2014 to 2023). "Interestingly, the GRIN2C gene, which encodes the GluN2C subunit, has several splice variants, and its expression is perturbed in some neurological disorders." (PMID 25426025, 2014).
GRIN2C also shares sentences with these, for which no sentence is quoted: cocaine addiction (4 papers); depression (4); ischemia (4); cognitive deficits (3); Cerebral ischemia (2); neurodevelopmental disorder (2); Stroke (2); alcoholism (1); amyotrophic lateral sclerosis (1); Aphasia (1); cancer (1); cognitive decline (1); colitis (1); developmental and epileptic encephalopathy (1); Dyskinesia (1); Encephalopathy (1); glioma (1); infarction (1); medulloblastoma (1); melanoma (1); memory impairment (1); mental retardation (1); multiple sclerosis (1); neuroblastoma (1); Obesity (1); Parkinson disease (1); peripheral nerve injury (1); Prader-Willi syndrome (1); prostate carcinoma (1); psychosis (1).
A further 4 diseases each share a sentence with GRIN2C in 1 paper.